SLC12A5 (solute carrier family 12 member 5)
Description:
Mediates electroneutral potassium-chloride cotransport in mature neurons and is required for neuronal Cl(-) homeostasis. As major extruder of intracellular chloride, it establishes the low neuronal Cl(-) levels required for chloride influx after binding of GABA-A and glycine to their receptors, with subsequent hyperpolarization and neuronal inhibition (By similarity). Involved in the regulation of dendritic spine formation and maturation.
Synonyms: hKCC2; KCC2; KIAA1176; DEE34; EIEE34; EIG14
Tractability: Small molecule: it belongs to a druggable protein family. Antibody: its Gene Ontology location is reachable by antibodies, with high confidence; UniProt places it where antibodies can reach, with medium confidence; UniProt predicts a signal peptide or a membrane-spanning region. PROTAC: its protein half-life has been measured; a small molecule that binds it is known.
Target class: Electrochemical transporter; SLC superfamily of solute carriers; Transporter; SLC12 family of cation-coupled chloride transporters
Chemical probes: ML077
Gene: Protein-coding gene on chromosome 20 (46,021,690 to 46,060,150, forward strand). Ensembl gene ENSG00000124140.
Subcellular location: Cell membrane; Cell projection, dendrite
Pathways (Reactome):
Transport of small molecules: Cation-coupled Chloride cotransporters
Gene Ontology:
Molecular function: chloride transmembrane transporter activity; potassium:chloride symporter activity; ammonium channel activity; chloride:monoatomic cation symporter activity; protein kinase binding; transmembrane transporter activity
Biological process: dendritic spine development; hypotonic response; intracellular chloride ion homeostasis; monoatomic ion transport; chloride transmembrane transport; chloride transport; potassium ion transmembrane transport; ammonium transmembrane transport; developmental process; intracellular pH reduction; postsynaptic neurotransmitter receptor diffusion trapping; potassium ion transport; regulation of postsynapse assembly; transmembrane transport
Cellular component: cell periphery; membrane; neuron projection; neuronal cell body; apical plasma membrane; plasma membrane; dendrite; dendrite membrane; glutamatergic synapse; perikaryon; postsynaptic specialization membrane
Genetic constraint (gnomAD): Loss-of-function variants: 18 observed, 118.66 expected, observed/expected ratio (o/e) 0.15, 90% interval 0.1 to 0.22. The upper end of that interval is the gene's LOEUF score, 0.22, which puts it in group 1 of 6, group 1 being the genes least tolerant of losing a copy. Missense variants: 838 observed, 1,504.3 expected, observed/expected ratio (o/e) 0.56, 90% interval 0.52 to 0.59. Synonymous variants: 571 observed, 574.99 expected, observed/expected ratio (o/e) 0.99, 90% interval 0.93 to 1.06.
Gene-disease validity (ClinGen):
ClinGen rates the evidence that SLC12A5 causes each of these diseases.
genetic developmental and epileptic encephalopathy (autosomal recessive): Limited. A complex neurodevelopmental disorder characterized by a range of developmental delays and epileptic encephalopathy phenotypes.
Homologues: Orthologues: chimpanzee SLC12A5 (99% identical), dog SLC12A5 (98% identical), pig SLC12A5 (98% identical), guinea pig SLC12A5 (98% identical), macaque SLC12A5 (98% identical), mouse Slc12a5 (97% identical), rat Slc12a5 (97% identical), rabbit SLC12A5 (90% identical), tropical clawed frog slc12a5 (87% identical), Drosophila melanogaster kcc (52% identical), Caenorhabditis elegans kcc-2 (44% identical), Drosophila melanogaster Ncc69 (25% identical), and 3 more. Paralogues in human: SLC12A7 (70% identical), SLC12A6 (68% identical), SLC12A4 (67% identical), SLC12A1 (26% identical), SLC12A2 (26% identical), SLC12A3 (25% identical), SLC12A9 (23% identical), SLC12A8 (14% identical).
Diseases named in the same sentence as SLC12A5 in open-access papers:
SLC12A5 is named in the same sentence as 159 diseases in open-access papers, as found by Europe PMC text mining. Sharing a sentence is not in itself a finding about the gene and the disease. The quoted sentences say what the papers report.
epilepsy (125 papers, 2011 to 2026). A brain disorder characterized by episodes of abnormally increased neuronal discharge resulting in transient episodes of sensory or motor neurological dysfunction, or psychic dysfunction. "Mutations in the human ortholog (KCC2) of the Slc12a5 gene mutations have been reported to cause febrile seizures and epilepsy in humans." (PMID 41433250, 2025). "This impaired Cl- extrusion has been proposed to underlie the mechanism by which SLC12A5 mutations cause epilepsy of infancy with migrating focal seizures (EIMFS)." (PMID 37704745, 2024). "Loss-of-function mutations in one allele of SLC12A5, encoding KCC2, produce a severe infantile-onset pharmaco-resistant epilepsy syndrome, epilepsy of infancy with migrating focal seizures (EIMFS)." (PMID 36295670, 2022). "In fact, fourteen different mutations of SLC12A5, the gene that encodes KCC2, have been identified in human epilepsy patients thus far." (PMID 36139484, 2022). "SLC12A5 (encoding the KCC2 protein) acts to stabilize nerve cell potential, and its reduced expression correlates with the development of epilepsy." (PMID 36588901, 2022). "Among the possible causes of chloride co-transporter unbalance, rare loss-of-function mutations of the SLC12A5 gene, encoding KCC2, were reported in patients with epilepsy." (PMID 34439564, 2021). "Here we show recessive loss-of-function SLC12A5 mutations in patients with a severe infantile-onset pharmacoresistant epilepsy syndrome, epilepsy of infancy with migrating focal seizures (EIMFS)." (PMID 26333769, 2015). "In the NFS network the epilepsy-associated gene SLC12A5 (alias KCC2) appears as a very relevant hub." (PMID 22022585, 2011). "Human patients with mutations in the SLC12A5 gene develop severe epilepsy soon after birth and developmental delay, while deletion of the SLC12A5 gene in mice causes hyperexcitability in the hippocampus, generalized seizures, temporal lobe epilepsy, and death shortly after birth." (PMID 40901055, 2025). "Since SLC12A5 has been included in epilepsy genetic screening panels, the number of KCC2 mutant variants identified has exponentially grown in recent years (see ∼900 SLC12A5 variants identified to date on ClinVar)." (PMID 39720463, 2024). "SLC12A5A/KCC2 is required for synaptic inhibition and loss of SLC12A5 is associated with epilepsy in a humans and in mice." (PMID 39405291, 2024). "The identification of various KCC2 mutations (encoded by SLC12A5) has further highlighted the association between KCC2 dysfunction and the development of epilepsy." (PMID 37704745, 2024). "More recently, KCC2 was identified as a genetically-validated target for epilepsy, intellectual disability, and autism spectrum disorder, and pathogenic mutations in human SLC12A5 gene were linked to psychiatric/mood disorders." (PMID 39720463, 2024). "According to the previous analysis, SLC12A2 was classified in cluster 8 related to demyelinating diseases, while SLC12A5 was classified in cluster 9 related to epilepsy." (PMID 36934242, 2023). "Mutations in SLC12A5 or SLC12A6, which encode KCC2 and KCC3, respectively, can cause brain disorders such as epilepsy, seizures, and sensorimotor neuropathy with agenesis of corpus callosum." (PMID 36557113, 2022). "Transgenic technology made it possible to analyze the gene sequence for human SLC12a5, a mutant human gene in patients with seizure disorders." (PMID 32010056, 2019). "Nevertheless, the geno-phenotype correlations between previously reported cases of SLC12A5 variants and the one reported here clearly overlap and underline the importance and sensitivity of KCC2 in the onset of early infantile epilepsies and neurodevelopmental disorders." (PMID 38660387, 2024). "Then, we compared mRNA levels of SLC12A2 and SLC12A5 in MS and epilepsy separately." (PMID 36934242, 2023).
epilepsy (continued). "Because KCC2 expression is required for GABA-dependent inhibitory synaptic transmission, mutations in the gene encoding KCC2 (SLC12A5) have been linked to several diseases that also arise from defects in GABA signaling, including epilepsy, schizophrenia, and autism spectrum disorders." (PMID 41433127, 2026). "Similarly, SLC12A5 mutations, affecting K-Cl cotransporter (KCC2) function, suggest a potential role for therapies aimed at restoring chloride homeostasis in neurons, such as bumetanide, which is under investigation for epilepsy management." (PMID 39767570, 2024). "SLC12A5 (KCC2) is the major chloride ion extrusion transporter, and its activity balance changes with SLC12A2 are highly related to epilepsy." (PMID 41425581, 2025). "In 8 patients, one or more epilepsy genes, GRIN2A, TET3, SCN1A, SCN8A, ADGRV1, DLG4, and SLC12A5, were found, and 12 patients had no genetic mutations." (PMID 38813507, 2023).
schizophrenia (39 papers, 2011 to 2026). A major psychotic disorder characterized by abnormalities in the perception or expression of reality. "Among these genes, GRIN2A and SLC12A5, implicated in schizophrenia and bipolar disorder, were significantly upregulated in TL PVALB neurons and in psychiatric disease patients’ brain." (PMID 38864245, 2024). "Both rs12624433 and SLC12A5 have been previously associated with major depression disorder and other mental disorders such as bipolar disorder or schizophrenia." (PMID 35886042, 2022). "For example, SULT4A1 and SLC12A5 are associated with schizophrenia." (PMID 33423377, 2021). "This included genes such as SLC12A5, which showed evidence of a genetically predicted effect on depression and neuroticism (P = 7.13 × 10−10 and P = 2.10 × 10−9 respectively), as well as PCDHA8, which provided evidence of genetically predicted effect on schizophrenia risk (P = 6.04 × 10−6)." (PMID 33481009, 2021). "Schizophrenia, a neuropsychiatric disorder, also has abnormalities in the GABAergic system where the ratios of three genes related to GABA signaling are increased: GAD1 (GAD67 and GAD25), SLC12A2 (NKCC1), and SLC12A5 (KCC2) in the prefrontal cortex." (PMID 36771011, 2023).
glioma (23 papers, 2014 to 2025). A benign or malignant brain and spinal cord tumor that arises from glial cells (astrocytes, oligodendrocytes, ependymal cells). "IDH1, as an essential biomarker in glioma patients, had missense mutation in most case of high SLC12A5 expression group, consistent with previous studies that glioma patients with IDH mutation had better outcomes." (PMID 38685685, 2024). "In TCGA glioma cohorts, low expression of SLC12A5 was significantly associated with increased tumour grade, IDH wild‐type and 1p/19q non‐codeletion status which were known molecular biomarkers." (PMID 38685685, 2024). "Together, these data showed that SLC12A5 was associated with immune infiltrations and had predictive value for immunotherapeutic response in glioma." (PMID 38685685, 2024). "Due to the association between elevated level of SLC12A5 and downregulation of cell proliferation and migration, we sought to evaluate the effect of SLC12A5 on these biological behaviours of glioma cells." (PMID 38685685, 2024). "Multiple independent glioma cohorts were included to analyse the characterization of SLC12A5 and found it was significantly associated with pathological features, prognostic value, genomic alterations, transcriptional landscape and drug response." (PMID 38685685, 2024). "Furthermore, underlying mechanisms by which SLC12A5 regulates the immunomicroenvironment of glioma remain to be explored." (PMID 38685685, 2024). "Therefore, we believe that EZH2 can inhibit glioma migration by regulating the expression of SLC12A5, and the mechanism underlying this phenomenon is likely due to the activation of the WNK1-OSR1-NKCC1 cascade." (PMID 38886655, 2024). "As somatic mutations could explain some molecular mechanisms involved in tumour progress, we classified patients in TCGA glioma cohort into two groups according to the median expression of SLC12A5 and compared the frequency of mutations between high‐expression group and low‐expression group." (PMID 38685685, 2024). "SLC12A5 expression inhibits the proliferation of glioma U251 MG cells, and the gene is a potential prognostic marker for GBM; activation of the co-transporter is an early sign of cell apoptosis." (PMID 40725030, 2025). "We predicted the relationship between SLC12A5 and glioma progression using data from multiple databases, and the results revealed a significant correlation between the expression of SLC12A5 and prognosis." (PMID 38886655, 2024). "SLC12A5 expression promotes prostate and liver cancer progression while inhibiting glioma cell proliferation." (PMID 38886655, 2024). "Collectively, our study provides a comprehensive characterization of SLC12A5 in glioma and supports SLC12A5 as a potential suppressor of disease progression." (PMID 38685685, 2024). "EZH2 facilitates glioma proliferation, migration, and invasion alongside promoting SLC12A5 DNA methylation." (PMID 38886655, 2024). "Published transcription data from glioma cell lines also confirmed highest expression level of SLC12A5 in normal human astrocytes." (PMID 38685685, 2024). "In conclusion, this study reaffirms the relationship between EZH2 and glioma progression, revealing EZH2's role in regulating SLC12A5 expression by methylating its promoter region, thereby impacting glioma progression." (PMID 38886655, 2024). "To further understand the effect of SLC12A5 on tumour malignancy and find potential drugs for therapy, we predicted drug sensitivity of total 198 drugs in TCGA glioma cohorts based on ridge regression model taking GDSC data sets as training set." (PMID 38685685, 2024). "Intriguingly, patients with higher expression of SLC12A5 presented longer overall survival (OS) in all glioma cohorts with significant log‐rank test in five of six data sets." (PMID 38685685, 2024). "Since SLC12A5 was overexpressed in low‐grade glioma and better prognostic subtypes, we set out to investigate the prognostic value of SLC12A5 across six independent cohorts." (PMID 38685685, 2024).
glioma (continued). "In summary, we identified SLC12A5, a candidate gene in glioma, from Hi‐C data which was decreased in tumour tissue and negatively correlated with tumour grade and malignant biological processes validated in vitro." (PMID 38685685, 2024). "Expression profiling of the peritumoral brain around IDHmut gliomas also showed upregulation of SLC12A5, THBS1, VEGFA, FOSL2, and SYNPO, as has been previously reported in epileptic brain tissue." (PMID 37104042, 2023). "It was reported that by regulating SLC12A5 expression, EZH2 activates the WNK1-OSR1-NKCC1 (lysine-deficient protein kinase-1—oxidative stress responsive 1—NKCC1) pathway to promote glioma migration and tumor invasion, while also promoting SLC12A5 DNA methylation." (PMID 41012498, 2025). "As gamma‐aminobutyric acid (GABA) was the main inhibitory neurotransmitter in the central nervous system and endogenous GABAA receptor activity had been reported to suppresses glioma growth, we further investigated the association between GABAA channel subunits and SLC12A5." (PMID 38685685, 2024). "In order to validate our findings above, we evaluated whether SLC12A5 was differentially expressed in clinical surgical samples and different glioma cell lines." (PMID 38685685, 2024). "Moreover, overexpression of SLC12A5 in glioma‐derived cell lines can suppress tumour cell proliferation and migration." (PMID 38685685, 2024). "It was particularly noteworthy that SLC12A5 was positively associated with GABAA receptor activity and low expression of SLC12A5 shaped an immunosuppressive microenvironment in glioma indicating its predictive value for glioma immunotherapy." (PMID 38685685, 2024). "Through meta‐analysis for combining cox results of three data sets, it demonstrated that SLC12A5 could be used as an independent prognostic factor for overall survival in glioma patients (HR = 0.53, p < 0.001)." (PMID 38685685, 2024). "Since the prognosis of elderly glioma is known to be poor, we explored the relationship between the expression of SLC12A5 and age of patients, which showed that the expression of SLC12A5 was weakly correlated with age of patients in four data sets indicating its independence." (PMID 38685685, 2024). "This may be the mechanism why overexpression of SLC12A5 in tumour cell suppress its proliferation and migration and low expression level of gene in high‐grade glioma, which need relatively extensive works to be validated in the future." (PMID 38685685, 2024). "Moreover, the prognosis of the high-expression group of SLC12A5 was significantly better than that of the low-expression group, indicating a significant correlation between SLC12A5 expression and prognosis in gliomas." (PMID 38886655, 2024). "Additionally, EZH2 promotes glioma proliferation, migration, and invasion by suppressing the expression of SLC12A5 through DNA promoter methylation." (PMID 38886655, 2024). "SLC12A5/TACC2/BSN/TLN2/ZDHHC8 was downregulated in patients with glioma with poor OS." (PMID 34660294, 2021). "However, the exact function of SLC12A5 in gliomas and the mechanisms by which it affects tumour progression remain unclear." (PMID 38685685, 2024). "As molecular subtypes were applied to differ survival ability in glioma patients where PN and CL had better prognosis than MES subtype, we also investigated their associations and found that MES subtype preferred low expression level of SLC12A5 in all four cohorts." (PMID 38685685, 2024). "By combining the expression of GABAA receptor and SLC12A5 to divide glioma patients into four groups, we found that OS of patients could be obviously distinguished under this stratification in which patients with high expression of GABAA receptor and SLC12A5 had the best outcome." (PMID 38685685, 2024). "Thus, we speculated that SLC12A5 had great application value in predicting the prognosis of glioma patients." (PMID 38685685, 2024).